CIST1 (colon, intestine and stomach enriched 1)
Gene: Protein-coding gene on chromosome 19 (18,249,950 to 18,255,395, reverse strand). Ensembl gene ENSG00000284797.
Subcellular location: Membrane
Gene Ontology:
Cellular component: membrane
Homologues: Orthologues: macaque CIST1 (84% identical), rat Cist1 (33% identical), mouse Gm3336 (32% identical).